SRBD1 (S1 RNA binding domain 1)
Description:
DNA- and histone-binding protein that localizes to the central axes of mitotic chromosomes. Promotes chromosome segregation by facilitating TOP2A recruitment to mitotic chromosomes, thereby preventing anaphase failure. During prophase, safeguards the decatenation process to avoid the formation of difficult-to-resolve DNA structures, preventing chromosome missegregation. Also contributes to the regulation of nucleus pulposus cell senescence.
Synonyms: FLJ10379
Tractability: PROTAC: UniProt records ubiquitination sites on it; ubiquitination databases record sites on it; its protein half-life has been measured.
Gene: Protein-coding gene on chromosome 2 (45,388,679 to 45,612,165, reverse strand). Ensembl gene ENSG00000068784.
Subcellular location: Nucleus; Nucleus, nucleolus; Cytoplasm; Chromosome
Subcellular location (Human Protein Atlas): Cytosol; Mitochondria
Gene Ontology:
Molecular function: structural constituent of ribosome; nucleic acid binding
Biological process: translation
Cellular component: chromosome; cytoplasm; nucleus; nucleolus
Genetic constraint (gnomAD): Loss-of-function variants: 77 observed, 106.71 expected, observed/expected ratio (o/e) 0.72, 90% interval 0.6 to 0.87. The synonymous counts are far from expectation, so gnomAD's model fits this gene poorly and the ratio says little. Missense variants: 1,327 observed, 1,189.9 expected, observed/expected ratio (o/e) 1.12, 90% interval 1.07 to 1.17. Synonymous variants: 496 observed, 417.11 expected, observed/expected ratio (o/e) 1.19, 90% interval 1.1 to 1.28.
Homologues: Orthologues: chimpanzee SRBD1 (99% identical), macaque SRBD1 (97% identical), rabbit SRBD1 (91% identical), pig SRBD1 (90% identical), guinea pig SRBD1 (87% identical), dog SRBD1 (82% identical), mouse Srbd1 (82% identical), rat Srbd1 (81% identical), tropical clawed frog srbd1 (64% identical), zebrafish srbd1 (44% identical), Drosophila melanogaster CG31156 (33% identical), Caenorhabditis elegans ZK973.1 (23% identical), and 1 more.
Diseases named in the same sentence as SRBD1 in open-access papers:
SRBD1 is named in the same sentence as 12 diseases in open-access papers, as found by Europe PMC text mining. Sharing a sentence is not in itself a finding about the gene and the disease. The quoted sentences say what the papers report.
glaucoma (8 papers, 2012 to 2025). Increased pressure in the eyeball due to obstruction of the outflow of aqueous humor. "Previous studies linked SRBD1 polymorphisms to an increased glaucoma risk, and an SRBD1-ALK fusion was described in adenocarcinoma patients, but little functional information exists for this largely unstudied protein." (PMID 39955279, 2025). "In this study, to verify recent genetic findings, we investigated the association between glaucoma in Shiba-Inu and Shih-Tzu dogs and polymorphisms of glaucoma candidate genes, SRBD1, ELOVL5 and ADAMTS10, using direct sequencing." (PMID 24040232, 2013). "Further investigation will be necessary to confirm the association of polymorphisms in the exon 4 and intron 1 regions of SRBD1 in human glaucoma patients." (PMID 24040232, 2013). "Three SRBD1 SNPs, rs8655283, rs22018514 and rs22018513 were significantly associated with glaucoma in Shiba-Inus, while rs22018513, a synonymous SNP in exon 4, showed the strongest association (P = 0.00039, OR = 3.03)." (PMID 24040232, 2013). "The results showed that SRBD1 polymorphisms play an important role in glaucoma pathology in both Shiba-Inus and Shih-Tzus." (PMID 24040232, 2013). "In Shih-Tzus, only rs9172407 in the SRBD1 intron 1 was significantly associated with glaucoma (P = 0.0014, OR = 5.25)." (PMID 24040232, 2013). "The present study found that a synonymous SNP (rs22018513) and intronic SNP (rs9172407) in SRBD1 were associated with glaucoma in Shiba-Inus and Shih-Tzus, respectively." (PMID 24040232, 2013). "Most studies on SRBD1 focus on its role in yeast, its function in the growth processes of specific plants, and its involvement in human diseases, especially its association with ocular diseases such as glaucoma." (PMID 38883609, 2024). "Moreover, canine glaucoma resulting from SRBD1 polymorphisms could be used as an excellent genetic animal model for human glaucoma and contribute significantly to the development of novel diagnostic and therapeutic options for glaucoma." (PMID 24040232, 2013). "Moreover, canine glaucoma resulting from SRBD1 polymorphisms could be a useful animal model to study human glaucoma." (PMID 24040232, 2013). "Three genes, SRBD1, CLIC5, and KLHL36, have been found to be involved in immune responses and reported to be associated with various phenotypes, such as glaucoma, neurological disorders, and carcinoma." (PMID 28355295, 2017). "In this study, we investigated the association between polymorphisms of the glaucoma candidate genes, SRBD1, ELOVL5, and ADAMTS10, and glaucoma in Shiba-Inus and Shih-Tzus." (PMID 24040232, 2013). "The aim of the present study was to assess the potential associations of polymorphisms in the candidate genes SRBD1, ELOVL5, and ADAMTS10, with the development of canine glaucoma." (PMID 24040232, 2013). "Therefore, SRBD1 may be a common susceptibility gene for glaucoma in humans and dogs." (PMID 24040232, 2013). "In 2010, the Writing Committee for the NTG Genetic Study Group of the Japan Glaucoma Society identified SNPs of SRBD1 (OR 2.80, p = 2.5 × 10−9) and ELOVL5 (OR 1.69, p = 4.1 × 10−6) as being associated with NTG in a cohort of 305 Japanese NTG patients and 355 controls." (PMID 33396423, 2020). "Therefore, detection of any common phenotypes in these glaucoma studies is important because it will help to clarify how SRBD1 affects the development of glaucoma." (PMID 24040232, 2013). "Therefore, we hypothesize that enhanced expression, leading to increased activity of SRBD1, which could induce apoptosis, could result in retinal ganglion cell death during the development of glaucoma." (PMID 24040232, 2013). "In contrast, SRBD1 polymorphisms were associated with canine glaucoma and human glaucoma independent of IOP, suggesting that SRBD1 polymorphisms may affect a common disease condition in canine and human glaucoma." (PMID 24040232, 2013).
normal tension glaucoma (2 papers, 2012 to 2017). "Another Japanese group carried out a separate GWAS, identifying S1 RNA binding domain 1 (SRBD1) and ELOVL fatty acid elongase 5 (ELOVL5) as new susceptibility genes for both normal tension glaucoma (NTG) and POAG (with the most highly associated SNPs being rs3213787 in SRBD1 and rs735860 in ELOVL5)." (PMID 22761751, 2012).
osteoporosis (1 paper, 2024). A condition of reduced bone mass, with decreased cortical thickness and a decrease in the number and size of the trabeculae of cancellous bone (but normal chemical composition), resulting in increased fracture incidence. "Further analysis using single-cell data allowed us to identify two key genes, FMNL2 and SRBD1, that are closely linked to both osteoclasts and osteoporosis." (PMID 38883609, 2024). "The analysis identified two key genes, FMNL2 and SRBD1, as playing pivotal roles, and found that the gut microbiome indirectly influences osteoporosis by regulating these genes." (PMID 38883609, 2024).
postmenopausal osteoporosis (1 paper, 2024). Metabolic disorder associated with fractures of the femoral neck, vertebrae, and distal forearm. "Furthermore, our research has identified several key genes (FMNL2 and SRBD1) whose expression in osteoclasts is significantly associated with the risk of postmenopausal osteoporosis." (PMID 38883609, 2024). "Additionally, key genes FMNL2 and SRBD1 were identified, offering new therapeutic strategies for the treatment of postmenopausal osteoporosis." (PMID 38883609, 2024).
viral infection (1 paper, 2024). "The effectiveness of the viral infection was assessed by immunofluorescence staining of SRBD1." (PMID 38169523, 2024).
degenerative diseases (1 paper, 2024). "However, the molecular mechanisms underlying SRBD1's involvement in degenerative diseases and cellular senescence remain largely unexplored." (PMID 38169523, 2024).
infection (1 paper, 2024). The state of being infected such as from the introduction of a foreign agent such as serum, vaccine, antigenic substance or organism. "However, the overexpression of NBR1 AAV alleviated these symptoms, and this beneficial effect was impeded by simultaneous infection with NBR1 and SRBD1 AAVs." (PMID 38169523, 2024).
SRBD1 also shares sentences with these, for which no sentence is quoted: adenocarcinoma (1 paper); carcinoma (1); neurological disorders (1); non-small cell lung carcinoma (1); tumour (1).